ENSG00000277966
Gene: Miscellaneous RNA gene on chromosome 7 (27,186,892 to 27,187,124, forward strand). Ensembl gene ENSG00000277966.
Gene Ontology:
Biological process: negative regulation of gene expression